EGFR (epidermal growth factor receptor)
Diseases named in the same sentence as EGFR in open-access papers (continued):
Sharing a sentence is not in itself a finding about the gene and the disease.
lung cancer (continued). "Thus, disrupting the sustained metabolic reprogramming in DTP cells may offer a strategy to mitigate acquired resistance to EGFR‐TKIs and prevent tumor recurrence in lung cancer patients." (PMID 40479551, 2025). "Non-smokers may develop lung cancer due to environmental factors, chronic inflammation, or genetic alterations, including EGFR mutations and ALK rearrangements." (PMID 40728967, 2025). "In this setting, a standard lung cancer diagnostic biopsy workup includes standard hematoxylin and eosin (H&E) sections, PDL1 immunohistochemistry (IHC), diagnostic IHC (for example, TTF-1, p40 and so on), ALK fusion IHC, rapid EGFR testing and comprehensive genomic sequencing." (PMID 40634781, 2025). "Therefore, although further studies are required to understand the generalizability of these findings, KID inhibition could potentially suppress lung cancer growth by disrupting its contributions to maintaining genome stability and EGFR signalling." (PMID 40002279, 2025). "Additionally, it is likely that they are not linked to primary resistance to EGFR TKIs in patients with lung cancer." (PMID 41153394, 2025). "The increase in disease burden among women may be due to the fact that lung cancer incidence in females is more often related to genetic susceptibility rather than smoking, with the EGFR mutation being the most common in East Asian females." (PMID 39840528, 2025). "However, non-smoking-related lung cancer, often linked to genetic mutations (e.g., epidermal growth factor receptor (EGFR), anaplastic lymphoma kinase receptors) and environmental exposures (e.g., radon, air pollution), accounts for 10–25% of cases globally." (PMID 41012430, 2025). "Given that mutant EGFR transduces survival signals, and affects cellular metabolism, a better understanding of the crosstalk between mutant EGFR-mediated signals and metabolic reprogramming is expected to facilitate the development of newer personalized therapeutics to manage lung cancer." (PMID 40940888, 2025). "Moreover, considering there are some widely-used biomarkers for lung cancer such as EGFR, KRAS, and PD-L1, combination of these factors with ZHX factors may provide more accurate and precise methods for prediction of patient survival." (PMID 41480542, 2025). "Targeting S100A9-ALDH1A1-RA signaling could suppress BMs in EGFR mutant lung cancer patients." (PMID 39998776, 2025). "However, there are also successful cases, such as the up-regulation of FASN expression in lung cancer, which is associated with poor prognosis, and inhibitors targeting FASN, such as orlistat, can inhibit tumor growth by preventing EGFR palmitoylation and enhancing its ubiquitination." (PMID 41281744, 2025). "Epidermal growth factor receptor (EGFR) mutations occur in 40%–60% of Southeast Asian patients and 10%–20% of Caucasian patients with lung adenocarcinomas and reach occurrences of 50%–60% in non-smoking patients with lung cancer." (PMID 40894225, 2025). "The results showed that Cryo-Radial had comparable diagnostic rates and epidermal growth factor receptor (EGFR) detection capabilities compared to CT-TTB, and that Cryo-Radial had the additional advantage of mediastinal staging and was a good diagnostic tool for lung cancer." (PMID 40661124, 2025). "Therefore, the development of new STAT3-targeted drugs may realize the dual targeting effect on CAF and lung cancer cells, and play the role of EGFR-TKI resistance reversal." (PMID 40703348, 2025). "Furthermore, similar results could be observed in two EGFR mutant lung cancer cells, H1975 (EGFR mutant in L858R and T790M) and HCC827 (an exon 19 deletion mutant)." (PMID 41254241, 2025).
lung cancer (continued). "In parallel, lung cancer in never-smokers has emerged as a distinct clinical and biological entity, more common in women and Asian populations, and strongly associated with oncogenic drivers such as EGFR mutations." (PMID 41142757, 2025). "Given the increasing reliance on genetic and biomarker testing (EGFR, ALK, ROS1, PD-L1, and KRAS mutations) for targeted treatments, the ability to perform molecular analysis on minimally invasive samples represents a significant advancement in lung cancer care." (PMID 40805957, 2025). "Therefore, we hypothesized that α-Mangostin exerts anti-lung cancer activity and has the advantage of low toxicity to further study its actions and mechanisms against NSCLC harboring EGFR T790M mutation." (PMID 40142069, 2025). "Notably, lung cancer patients across all subtypes—including those with and without EGFR mutations and those with TKI resistance—consistently exhibited elevated levels of glycine and reduced levels of tryptophan and inositol compared to healthy controls." (PMID 41142757, 2025). "Non–small cell lung cancer harboring a SMARCA4/SMARCA2 deficiency has no established treatment because it is mutually exclusive to genetic abnormalities such as EGFR mutations and anaplastic lymphoma kinase (ALK) and RET fusions, for which there are established treatments." (PMID 39625239, 2025). "Secondary mutations in the EGFR driver gene are a primary cause of resistance to EGFR-TKIs 2, 3; in addition, other mutations including BRAF, PIK3CA, HER2 or c-MET amplifications, which were independent of EGFR pathway, account for 5-20% in EGFR-TKIs resistant lung cancer." (PMID 39744423, 2025). "Besides, both MS‐275 and GM‐protac could inhibit the expression of HER‐2, Axl, c‐Met, and NF‐κB, but G‐protac had a weaker effect on these proteins, indicating the necessary of HDAC and EGFR signaling pathway inhibition on osimertinib‐resistant lung cancer." (PMID 40842076, 2025). "A nationwide case-referent study in Taiwan reported that prolong PM2.5 exposure increased the risk of adenocarcinoma-related lung cancer in both females and males, in people with and without EGFR mutations, and in both early and advanced stages of adenocarcinoma-related lung cancer." (PMID 39578555, 2025). "Computational methods to detect EGFR mutations that can be deployed with little cost, rapid TAT and automated implementation while preserving tissue for comprehensive genomic sequencing have the potential to greatly improve the clinical workflow for lung cancer diagnostic biopsies." (PMID 40634781, 2025). "Finally, we included 10 well-known cancer-related genes (or their hotspot-containing exons) listed as most frequently mutated in lung cancer (BRAF,EGFR,ERBB2,HRAS,KRAS,MAP2K1,MET,NF1,NRAS, and RIT1) in the panel to serve as internal controls for highly mutated regions." (PMID 40867048, 2025). "Thus, it is crucial to improve the efficacy of EGFR‐TKIs against mutated tumor cells to prolong patient survival from the beginning of treatment, and selecting low‐toxicity, high‐efficiency drugs to alleviate resistance to EGFR‐TKIs during the treatment of lung cancer is a solution." (PMID 39907159, 2025). "It will also be important to explore whether the importance of YAP/TEAD activation in PRAD lineage maintenance reported here extends to other tumor settings in which lineage plasticity is also a mechanism of acquired resistance, such as EGFR-mutant lung cancer." (PMID 41509338, 2025). "Similarly, targeted therapies such as EGFR inhibitors can induce NED directly in lung cancer." (PMID 39941808, 2025). "Similarly, Smurf2 stabilizes EGFR in lung cancer and cervical cancer, indicating that Smurf2 could be an oncogene in lung and cervical cancers." (PMID 40978141, 2025).
lung cancer (continued). "Moreover, such an interaction was revealed in four out of five tested non‐iCCA cancer cell lines, and silencing LAMC2 also reduced the EGFR protein translation, especially in pancreatic cancer cell line Panc‐1, lung cancer cell line H1975 and colorectal cancer cell line HCT‐116." (PMID 38526177, 2024). "Furthermore, earlier research found that an elevated level of STAT3 phosphorylation may trigger EGFR-TKI resistance in lung cancer patients." (PMID 39264588, 2024). "Notably, up to 90% of East Asian women with lung cancer who have never smoked were found to have EGFR mutations in their tumors." (PMID 39596025, 2024). "Moreover, EGFR present in exosome membranes could also represent a possible marker for lung cancer diagnosis." (PMID 38338696, 2024). "Similar to a previous report, there were some patients (8% of total lung cancer patients) with EGFR mutations that could not be detected by RT-PCR." (PMID 38668785, 2024). "However, our study provides valuable real-world data regarding EGFR-mutant lung cancer." (PMID 38347279, 2024). "Although there are no established guidelines for screening lung cancer in asymptomatic individuals with known EGFR germline mutations, it is recommended that family members who have been diagnosed with EGFR germline mutations undergo regular monitoring through CT scans." (PMID 39160638, 2024). "In lung cancer, metabolic alterations in sphingolipids were found to affect cancer progression, development, and drug resistance, but until now no data in the literature associate resistance to EGFR-TKIs with aberrant ceramide glycosylation." (PMID 38499619, 2024). "However, lung cancer patients with HER2 mutations developed more brain metastases during treatment than patients with KRAS (28% vs. 8%, hazard ratio [HR] 5.2, P < 0.001) and EGFR mutations (28% vs 16%, HR 1.7, P = 0.06)." (PMID 39012378, 2024). "Do patients diagnosed with EGFR-mutant non–small cell lung cancer (NSCLC) receiving osimertinib have higher cancer therapy–related cardiac events (CTRCEs) compared with those receiving other epidermal growth factor receptor tyrosine kinase inhibitors (EGFR TKIs)?" (PMID 39636639, 2024). "Therefore, the inhibition of EGFR can inhibit the progression of lung cancer." (PMID 39682819, 2024). "EGFR is a receptor tyrosine kinase that participates in the regulation of cell growth, differentiation, survival and metastasis, Studies have shown that many tumorigenesis, such as lung cancer, lung adenocarcinoma and cholangiocarcinoma, are closely related to overexpression or mutation of EGFR." (PMID 38533261, 2024). "Lung cancer can be induced by the nitrosamine impurities, as they have the ability to stimulate proliferation, migration, and cancer cell survival by modulating G-protein signaling, nicotinic acetylcholine receptor (nAchR) signaling, and epidermal growth factor receptor (EGFR) signaling." (PMID 38799236, 2024). "However, it has been shown that Infigratinib can sensitise EGFR mutant and drug-tolerant lung cancer cells, and that dual EGFR and FGFR inhibition may prevent and overcome drug resistance." (PMID 38177929, 2024). "In a real-world study of patients with lung cancer in a community-based Ontario hospital, a median turnaround time of 36.5 days (interquartile range: 29.5–47 days) was reported for tissue testing results (EGFR and ALK), with only 20% of patients having biomarker results at the first consultation." (PMID 39451753, 2024). "Interestingly, we observed tumor formation in BCL2L1 KO mouse lungs, suggesting that BCL2L1 plays a crucial role in drug resistance but has no impact on tumorigenesis in EGFR-mutated lung cancer." (PMID 39122703, 2024). "Lung cancer patients with EGFR mutations tend to have little or no smoking history." (PMID 39280252, 2024). "Therefore, inhibition of MAPK signaling by EGFR-TKI may facilitate lineage switching in EGFR-mutant lung cancer cells." (PMID 39456595, 2024).
lung cancer (continued). "However, their presence alone is insufficient for tumorigenesis: Hill and colleagues have recently reported that 18% of normal lung tissue samples in patients both with and without lung cancer were found to carry EGFR mutations." (PMID 39021764, 2024). "A separate study in lung cancer cells harboring epidermal growth factor receptor (EGFR)-activating mutations found that preferential expression of DDX3X induced a cancer stem cell-like phenotype, increasing EMT as well as a loss of sensitivity to EGFR-tyrosine kinase inhibitors." (PMID 38539466, 2024). "Using a novel cohort of in vivo PDX models of MET pathway activation with acquired resistance to osimertinib in EGFR-mutant lung cancer, we demonstrate that phospho-MET may be a clinically relevant assay to guide treatment selection with osimertinib and savolitinib combination." (PMID 38276867, 2024). "Therefore, a TC combination regimen with chemotherapeutic drugs or EGFR-targeted therapeutics might help patients overcome drug resistance in lung cancer cells." (PMID 38539505, 2024). "Taken together, DHA could induce selective anti-lung cancer efficacy through binding to EGFR and thereby abolishing the NRAS signaling pathway, thus leading to DNA damage, which provides a novel theoretical basis for phytomedicine molecular therapy of malignant tumors." (PMID 38778121, 2024). "Notably, an international multicenter study with a large cohort of cases developed a DL model based on the entire lung, which achieved an AUC of 0.812 in predicting EGFR status in lung cancer and successfully stratified progression‐free survival in patients treated with EGFR‐TKI." (PMID 39252824, 2024). "Nowadays, the first-line treatment of patients with lung cancer harbouring a classical EGFR mutation (exon 19 deletion or L858R mutation in exon 21) is usually osimertinib, a third-generation irreversible EGFR TKI, with or without chemotherapy as the first-line therapy." (PMID 38891886, 2024). "The efficacy of epidermal growth factor receptor (EGFR)-tyrosine kinase inhibitors (EGFR-TKIs) in treating EGFR mutant advanced lung cancer has been established Furthermore, attempts are being made to explore the use of EGFR-TKIs as adjuvant therapy for earlier stages of lung cancer." (PMID 39255996, 2024). "Although five TKIs targeting EGFR mutations (afatinib, dacomitinib, erlotinib, gefitinib, and osimertinib) are approved in Japan, none are recommended in the Japan Lung Cancer Society clinical practice guidelines for the treatment of patients with EGFR exon 20 insertion mutations." (PMID 39190099, 2024). "We found that patients with high CD151 levels had a higher rate of disease‐specific death from lung cancer than those with low CD151 levels (p = 0.045), supporting our conclusion that CD151 overexpression is of prognostic value for lung cancer patients without EGFR mutations." (PMID 38982031, 2024). "Molecular alterations such as EGFR mutations, ALK rearrangements, ROS1 rearrangements, RET rearrangements, NTRK fusions, MET mutations, KRAS mutations, BRAF V600E mutations, and HER2 mutations are the contributing factors that underlie the aggressiveness of lung cancer." (PMID 38474400, 2024). "Unlike the majority of persisters (noncycling persisters) in lung cancer cells with EGFR mutation undergoing EGFR tyrosine kinase inhibitor (Osimertinib) treatment, this rare lineage not only emerges but also continues to proliferate under drug pressure instead of remaining arrested." (PMID 39572229, 2024). "As for the efficacy of neoadjuvant immunotherapy combined with chemotherapy in EGFR-mutant patients, there is currently no prospective evidence to suggest that perioperative immunotherapy benefits patients with resectable, driver mutation-positive lung cancer." (PMID 39640262, 2024). "Therefore, the use of ferroptosis inducers in EGFR-TKI resistant lung cancer may be another breakthrough." (PMID 38515565, 2024).
lung cancer (continued). "Unique genomic characteristics of human never-smoker lung cancer include somatic activating point mutations or fusions affecting EGFR (45%), anaplastic lymphoma kinase (ALK; 5–11%), ROS (1.5–6%), human epidermal growth factor receptor 2 (HER2; 3–5%) and rearranged during transfection (RET; 2%)." (PMID 39902337, 2024). "Furthermore, the surface proteins of exosomal membranes, such as EGFR, placental alkaline phosphatase, epithelial cell adhesion molecule (EpCAM), and Alix, serve as noteworthy indicators of long-term survival in patients with lung cancer." (PMID 39459055, 2024). "Based on these data, we speculated that the wt-EGFR inhibitor BA might be a potential sensitizer mediating resistance to EGFR-TKIs in lung cancer cells expressing wt-EGFR and that treatment with BA plus EGFR-TKI is a promising combination therapy for intractable NSCLC harboring wt-EGFR." (PMID 38764025, 2024). "The interplay of DUSP22 with EGFR and PD-L1 in lung cancer cells remains unclear." (PMID 38877005, 2024). "This cohort study examines whether osimertinib is associated with a higher incidence of cardiac toxic effects compared with earlier-generation epidermal growth factor receptor tyrosine kinase inhibitors among patients in Taiwan with EGFR-mutant non–small cell lung cancer." (PMID 39636639, 2024). "However, following targeting of the 72 resistance genes we observed that only a very limited subset targeted for silencing were capable of preserving signalling through the PI3K, MAPK, and mTOR pathways, all known mediators of resistance in EGFR mutant lung cancer." (PMID 38658677, 2024). "When EGFR-tyrosine kinase inhibitors (TKI)-treated EGFR-mutant cells were cultured in vitro with anti-CD24 antibodies, monocyte-derived macrophages promoted antibody-dependent cell phagocytosis (ADCP), indicating that CD24 may be a therapeutic target for EGFR-mutant lung cancer." (PMID 38279998, 2024). "In addition, the application of ACSL inhibitors or ACSL knockdown may sensitize lung cancer cells to Gemcitabine or EGFR-TKIs." (PMID 38539505, 2024). "Detection of epidermal growth factor receptor (EGFR), epithelial-to-mesenchymal transition (EMT) mutation, exosomes, bone resorption stimulating factor (BRSF) and analysis of ALK, ROS1, RET and NTRK translocation have been incorporated into the diagnosis or treatment of lung cancer." (PMID 38560274, 2024). "In addition to EGFR T790M mutations being associated with familial clustering of lung cancer, this variant has also been linked to non-tobacco users." (PMID 38539485, 2024). "However, relevant studies on lung cancer have mainly focused on EGFR- NSCLC, and the impact of the gut microbiota and metabolites on EGFR + NSCLC remains unknown." (PMID 38566102, 2024). "Although the primary purpose of the CRISPR screens was to detect resistance genes, whether, through overexpression or silencing, the same data can be analysed for genes that when silenced have the opposite effect – enhancing the effect of osimertinib or gefitinib in EGFR mutant lung cancer cells." (PMID 38658677, 2024). "In addition to ethnicity, EGFR mutations in lung cancer are also associated with female sex and non-smoking status, consistent with our results." (PMID 38679659, 2024). "In a previous study, we identified aas 1‒46 of ESM1 as crucial for the association with the extracellular domain of the EGFR and developed two peptide fragments of ESM1, including 1‒27 (peptide 1) and 26‒46 aas (peptide 2), to block the interaction of ESM1 and EGFR in lung cancer cells." (PMID 39309430, 2024). "However, combining ABT-263 with osimertinib has not shown striking positive effects for patients with EGFR-mutated lung cancer after EGFR-TKI failure." (PMID 39122703, 2024). "Our study further suggests that GRP78/BiP inhibitors may offer a therapeutic approach to suppress EGFR in various human lung cancer cells without the limitations of targeting specific mutations." (PMID 37487081, 2023).